MEF2C (myocyte enhancer factor 2C)
Diseases named in the same sentence as MEF2C in open-access papers (continued):
Sharing a sentence is not in itself a finding about the gene and the disease.
epilepsy (continued). "It should be noted that both MEF2C and RBPJ have been associated with intellectual disability and seizure disorders, matching the SOX18 E137K Geno2MP neurological phenotypes." (PMID 36672963, 2023). "Due to involvement of MEF2C in many processes during neural developmental stages, functional disruption of MEF2C results in various neurological symptoms, among which epilepsy is a common symptom." (PMID 34991657, 2022). "Besides, LncRNAUCA1 (long-chain non-coding RNA urothelial carcinoma associated 1) inhibits inflammatory responses to epilepsy by modulating miR203-mediated regulation of the MEF2C/NF-κB signaling pathway, therefore, it may be a potential therapeutic target for epilepsy." (PMID 34991657, 2022). "In a review involving 19 patients with MEF2C-related epilepsy, seizures were established to have occurred in the first 12 months of life in 12 patients (63%)." (PMID 34991657, 2022). "We noted some non-specific phenotypic overlap between our individuals and those with variants in MEF2C (MIM: 613443), including DD/ID, stereotypic movements, epilepsy, and variable MRI brain scan anomalies." (PMID 33537682, 2021). "MEF2C haploinsufficiency has been shown to be responsible for severe cognitive deficit with stereotyped movements, epilepsy, and/or cerebral malformations." (PMID 34621295, 2021). "Mutations in TCF4, MEF2C, UBE3A, ZEB2 or ATRX cause phenotypically overlapping, syndromic forms of NDDs with severe intellectual disability, epilepsy and microcephaly." (PMID 31988313, 2020). "The haploinsufficiency of MEF-2C reported in patient and mouse models leads to severe mental retardation, epilepsy and cerebral malformations, and also the mice exhibited severe hyperkinesis." (PMID 31105874, 2019). "Transcription factor MEF2C regulates multiple genes linked to autism spectrum disorder (ASD), and human MEF2C haploinsufficiency results in ASD, intellectual disability, and epilepsy." (PMID 29133852, 2017). "The involvement of MEF2C has also been reported for epilepsy." (PMID 36834528, 2023). "MEF2C-related epilepsy usually occurs during infancy or early childhood." (PMID 34991657, 2022). "Another study documented a 9.68% rare functional variation of MEF2C in ASD patients with epilepsy, but not in ASD patients without epilepsy, indicating that MEF2C functional variation significantly increased the risk of epilepsy in ASD." (PMID 34991657, 2022). "Rett's syndrome is characterized by severe mental retardation, epilepsy, absence of speech and cerebral malformations, and MEF-2C polymorphisms have been found in patients with Rett's or severe Rett-like encephalopathies." (PMID 31105874, 2019). "More than half patients with MEF2C haploinsufficiency experienced epilepsy." (PMID 30376817, 2018). "Exome sequencing has identified mutations in the SIK1 gene in developmental epilepsies, which is consistent with the important roles for SIK1 targets including MEF2C and CRTC1/CREB transcriptional target genes in neurodevelopment and epilepsy pathogenesis." (PMID 36731029, 2023). "MEF2C is also involved in the development of various neuropsychiatric disorders, such as autism spectrum disorders (ASD), epilepsy, schizophrenia and Alzheimer’s disease (AD)." (PMID 34991657, 2022). "LncRNA UCA1 was downregulated in epilepsy, whereas the UCA1/miR-203/MEF2C axis inhibited the activation of NF-κB signaling pathway and IL-6, TNF-α, and Cox-2 levels in epilepsy." (PMID 33776905, 2021). "Here, we found enrichment for binding sites of ARNTL, important for circadian rhythm associated with BD, MEF2D, involved in neuronal differentiation and PD, and MEF2C, involved in ASD, ID, and epilepsy among others." (PMID 27014338, 2016). "In ASD cases with epilepsy or tics, 25.81% and 9.68% carried rare functional variants in CNTNAP2 and MEF2C, respectively, whereas in ASD cases without epilepsy or tics, only 2.78% and 0% carried rare functional variants in CNTNAP2 and MEF2C, respectively." (PMID 30763456, 2019).
epilepsy (continued). "For example, altered calcium homeostasis seems to be responsible for an abnormal neuronal development and generates epilepsy; and tubulin, ERM and MEF2C are some of the altered proteins related to cytoskeletal abnormalities that are present not only in RTT, but also in Angelman syndrome." (PMID 31409060, 2019). "Heterozygous variants of MEF2C can result in autosomal dominant mental retardation 20 (MRD20), which is mainly characterized by severe mental retardation, absence of speech, epilepsy, and autistic behavior." (PMID 30763456, 2019). "Developmental regression, autism, and epilepsy can also be seen in disorders of ion channels (i.e., Dravet syndrome), impairments of receptor expression (i.e., GRIN1), transcription factors (i.e., MEF2C), axonal guidance (i.e., NTNG1), and ubiquination (i.e., RHOBTB2)." (PMID 37511662, 2023). "Furthermore, haploinsufficiency of MEF2C also results in a form of severe mental retardation, with absent speech, hypotonia and epilepsy." (PMID 24058414, 2013).
leukemia (31 papers, 2007 to 2026). A malignant (clonal) hematologic disorder, involving hematopoietic stem cells and characterized by the presence of primitive or atypical myeloid or lymphoid cells in the bone marrow and the blood. "MEF2C (often deregulated and associated with recurrence in leukemia) and ZEB1 (shown to modulate hematopoietic stem cell fates) are also inactive in the blood (TF activity -0.882 and -1.532, respectively)." (PMID 38165902, 2024). "MEF2C plays a role in immunity and leukemia development, and was implicated as an oncogene in various hematological and solid cancers." (PMID 30670970, 2018). "Functional studies using mouse leukemia models demonstrate that Mef2c is a potent oncogene, causing fully penetrant AML in cooperation with SOX4." (PMID 26487643, 2015). "In mouse models of myeloid leukemia, Mef2c was able to act as a co-operating oncogene in combination with either Irf8 deficiency or Sox4 activation, though it was insufficient to independently drive leukemia development." (PMID 26506234, 2016). "Mouse leukemia models studies found that MEF2C is a potent oncogene, which controls proliferation of hematopoietic cells under stressful conditions in cooperation with SOX4 resulting in fully penetrant AML." (PMID 38710877, 2024). "It was found that MEF2C-dependent leukemia was sensitive to chemical inhibition-targeted SIK activity." (PMID 35528167, 2022). "MEF2C is a transcription factor which is specifically expressed in muscle and neuronal lineages and is commonly upregulated in leukemia." (PMID 36059448, 2022). "In order to understand the correlation between MEF2C and different leukemias, we explored BloodSpot4 “a database of gene expression profiles and transcriptional programs for healthy and malignant hematopoiesis” looking for MEF2C expression." (PMID 34249950, 2021). "In contrast, deregulated MEF2D activity, with activation of HDAC9 and resulting inhibition of MEF2C were characteristic of this form of leukaemia." (PMID 27824051, 2016). "Our data suggest synergistic inputs of AUTS2 and MEF2C in lymphopoiesis and leukemia (de)regulating NKL homeobox gene MSX1." (PMID 27322685, 2016). "To test this possibility, we determined the protein levels of HDAC3, MEF2C and c-Myc in leukemia and lymphoma cell lines." (PMID 25675295, 2015). "The transcripts all initiated in the viral 5′LTR and spliced into the first coding exon of Mef2c, similar to what is reported for other leukemias with Mef2c insertions." (PMID 19461887, 2009). "Remarkably, 3 tumors also have insertions in intron 2 of Mef2c, which is a transcription factor oncogene that cooperates with Sox4 in leukemia induction." (PMID 19461887, 2009). "Notably, TCF3::HLF directly regulates MEF2C expression through its enhancer, as interference disrupted MEF2C transcription and inhibited leukemia propagation." (PMID 42090509, 2026). "As well as, MEF2C phosphorylation has resulted in leukemia stem cell maintenance." (PMID 38710877, 2024). "In addition, MEF2C is needed for the mouse leukemias growth that is induced by MLL-AF9 as it regulates G2/M transition in the cell cycle." (PMID 38710877, 2024). "Among the TFs that we and others identified to be selectively essential and overexpressed in KMT2A-rearranged leukemia, MEF2C, RUNX2, and MEIS1 are well-established direct targets of KMT2A fusion oncoproteins, prompting us to consider that one of these TFs drives IRF8 overexpression." (PMID 35301220, 2022). "It will be important to determine how aberrant co-expression of such oncogenic regulatory complex co-factors is induced in leukemia cells by diverse oncogenes, such as for example by kinase-dependent dysregulation of transcription factor assembly recently described for MEF2C and LYL1." (PMID 33527899, 2021). "High expression of ARID2, JMJD1C, MBNL1, MEF2C, or RUNX2 alone is associated with at least one indicator of poor prognosis in ALL patients, and CPEB2, MBNL1, RUNX2, and ZEB2 are all specifically overexpressed in MLL-FP leukemias." (PMID 28076791, 2017).
leukemia (continued). "It is unclear how ectopic induction of Mef2c promotes leukaemia progression, and whether it regulates DNA repair that could lead to survival advantage and/or therapy resistance." (PMID 27507714, 2016). "Given the strong association between disease risk and MEF2C expression, one might attribute the worse outcome for patients with high MEF2C expression to the lower prevalence of leukemias with more favorable prognoses in this subgroup." (PMID 26487643, 2015). "Furthermore, MEF2C may functions as a key regulator of cytokine signaling-2 suppressor in normal hematopoiesis and leukemia that may confer features of leukemic stemness to a neoplastic hematopoietic clone." (PMID 38710877, 2024). "Thus, MEF2C may activate expression of HOXA9 in non-KMT2Ar leukemias, while the role of MEF2D is restricted to KMT2Ar AML." (PMID 35301220, 2022). "Finally, we performed gene expression studies in MLL-AF9 and MLL-AF6 transformed bone marrow cells and found that genes highly relevant to MLL leukemia (Hoxa5, Hoxa9, Hoxa10, Meis1, and Mef2C) were expressed at much lower levels in the ΔSET Ash1l versus WT Ash1l cells." (PMID 33990599, 2021). "In addition, MEF2C has previously been identified as a possible leukemia-related oncogene." (PMID 33075110, 2020). "MEF2C, a member of the MADS family of transcription factors, regulates hematopoietic self-renewal and differentiation, supports the proliferation of leukemias, and is associated with increased risk of relapse in leukemia patients as its phosphorylation leads to chemotherapy resistance." (PMID 32477331, 2020). "Our data indicate that high MEF2C expression identifies a subset of pediatric and adolescent AML patients with adverse-risk disease features and, consequently, significantly increased risk for primary treatment failure, relapse, and poor leukemia-free and overall survival." (PMID 26487643, 2015). "In addition, Mef2c is required for the growth of mouse leukemias induced by MLL-AF9." (PMID 26487643, 2015). "Since MEF2C is normally downregulated during the ETP stage, prolonged or enhanced MEF2C expression may cause supraphysiological IL-7R signaling and BCL2 expression that contributes to the arrest, survival, and enhanced growth of ETP cells resulting in leukemia." (PMID 35536646, 2022). "As expected, the group of genes we identified as the most frequent KMT2A fusion targets across our collection of samples included several genes that are known to be required for KMT2Ar leukemia, including HOXA9, MEIS1, MEF2C, MBNL1 and JMJD1C25–29." (PMID 34663924, 2021). "While MEF2C is a well-established transcriptional dependency of KMT2A-rearranged AML, the role of MEF2D in leukemia has remained relatively unexplored." (PMID 35301220, 2022). "Taken together, low dose MLL1 and DOT1L inhibitors downregulate different, yet partially overlapping sets of genes (with FLT3, MEF2C, and PIM1 in common), that are necessary for MLL-rearranged leukemia, consistent with the synergism arising from largely distinct pathways." (PMID 34263728, 2021). "In AML, MEF2C has been found to be overexpressed in distinct molecular subsets of adult onset AML, including mixed lineage leukemia (MLL) gene-rearranged and ectropic virus integration site 1 (EVI1)-overexpressing leukemias." (PMID 26487643, 2015). "However, dependency on MEF2C appears to have no significant selectivity toward KMT2Ar cell lines, and MEF2C is not as strongly overexpressed in KMT2Ar leukemias in the BeatAML data set." (PMID 35301220, 2022). "In contrast to MEF2C and MEF2D, MEF2A and MEF2B have not been implicated in leukemia development." (PMID 26506234, 2016). "Thus, a network linking MEF2C, IL7R, STAT5 and AUTS2 may play a role in two cellular contexts: T-cell differentiation/leukemia and brain development/autism-related disorders." (PMID 27322685, 2016).
leukemia (continued). "Interestingly, RUNX2, MBNL1, JMJD1C, SENP6, MEF2C, and ZEB2 are also hypomethylated in MLL-FP samples compared to either normal cells or other leukemias (not shown)." (PMID 28076791, 2017).
Intellectual disability (30 papers, 2010 to 2025). "Haploinsufficiency of MEF2C is known to cause a syndrome characterized by intellectual disability and neurological abnormalities." (PMID 36070311, 2022). "Loss-of-function mutations in MEF2C, which encodes an activity-dependent transcription factor, are implicated in intellectual disability, ASD and schizophrenia." (PMID 34617509, 2021). "Humans with mutations in MEF2C exhibit severe intellectual disabilities, loss of muscle tone, mild craniofacial dysmorphologies and severe seizures." (PMID 34137816, 2021). "Pathogenicity of MEF2C overexpression is still unclear as only four patients with mild intellectual deficiency carrying 5q14.3 microduplications containing MEF2C are described in the literature." (PMID 31375103, 2019). "Mef2c haploinsufficiency is implicated in behavioral deficits related to autism, schizophrenia, and intellectual disability." (PMID 30276662, 2019). "Prior studies have shown MEF2C haploinsufficiency, deletions, and point mutations to be associated with seizures, cortical malformations, intellectual disability, and hyperkinesis." (PMID 30006604, 2018). "Numerous genetic variants associated with MEF2C are linked to autism, intellectual disability (ID) and schizophrenia (SCZ) – a heterogeneous collection of neurodevelopmental disorders with unclear pathophysiology." (PMID 27779093, 2016). "Recent genetic studies have linked human MEF2C to a syndromic form of intellectual disability with autistic features, and single-nucleotide polymorphisms (SNPs) near MEF2C produce significant risk for SCZ, which highlight the importance of this gene for normal brain development and function." (PMID 27779093, 2016). "Consequently, establishing whether expression of AK082072 transcriptionally regulates Mef2C, a gene implicated in autism and intellectual disability phenotypes, warrants detailed investigation." (PMID 20624288, 2010). "MEF2C is also highly relevant to cortical midline DMN circuitry and is highly associated with male-biased conditions such as autism and intellectual disability." (PMID 30104728, 2020). "MEF2C is a critical transcription factor in neurodevelopment, whose loss-of-function mutation in humans results in MEF2C haploinsufficiency syndrome (MHS), a severe form of autism spectrum disorder (ASD)/intellectual disability (ID)." (PMID 39349966, 2025). "Mutations of MEF2C have been identified in individuals with ASD and intellectual disabilities." (PMID 38281278, 2024). "Mef2c is a high confidence risk gene for ASD, intellectual disability(ID) and schizophrenia." (PMID 32452758, 2020). "In this study, five MEF2C mutations were identified in RTT (−like) syndrome or non-syndromic intellectual disability patients, of which three mutations were novel." (PMID 30376817, 2018). "Typical clinical manifestations in patients with MEF2C gene mutations encompass global developmental delay, intellectual disability, absent speech, poor eye-contact and various minor brain anomalies on MRI." (PMID 30376817, 2018). "These MEF2C haploinsufficient patients present with a number of symptoms, including motor abnormalities (e.g. dyskinesias, stereotypies and hyperactivity), impairments in reciprocity, severe deficits in verbal communication, and severe intellectual disability." (PMID 27779093, 2016). "In addition to ASCL1 and NEUROG2, other neurodevelopmental transcriptional regulators such as, MEF2C (syndromic mental retardation) and ZEB2 (MWS) were also differentially expressed in TCF4-depleted cells." (PMID 24058414, 2013). "Furthermore, haploinsufficiency of the MEF2C gene has been described due to larger deletions as well as disease causing variants in patients with intellectual disability, absence of speech and seizures." (PMID 31235867, 2019).
Intellectual disability (continued). "Subsequently, murine brain-specific knockout of MEF2C at early developmental stages was shown to display electrophysiological, histological, and behavioral deficits reminiscent of Rett syndrome (RTT), a severe form of ASD and intellectual disability (ID)." (PMID 39349966, 2025).